CD9 (CD9 molecule)
Diseases named in the same sentence as CD9 in open-access papers (continued):
Sharing a sentence is not in itself a finding about the gene and the disease.
hepatocellular carcinoma (15 papers, 2014 to 2025). A malignant tumor that arises from hepatocytes. "It looks like CD9 can promote tumor growth in different types of cancers, but an in vivo experiment has shown a contradictory result that the knockout of CD9 in hepatocellular carcinoma can facilitate cancer development instead." (PMID 35757760, 2022). "In contrast, CD9 showed low expression levels in all three cell lines and was 2.5-fold higher in fibroblasts than in the hepatoma cells." (PMID 35612284, 2022). "The membrane protein CD9 from mouse hepatocellular sEVs can be fused with the therapeutic miRNA, allowing the miRNA to be encapsulated in sEVs and delivered to hepatocellular carcinoma cells for treatment." (PMID 34094979, 2021). "In contrast, naïve and infected hepatoma cells showed comparable spread following stimulation with anti-CD9, anti-CD151 or -Beta-1 integrin." (PMID 24662676, 2014). "Likewise CD9 overexpression in hepatocellular carcinoma inhibited proliferation in vitro and in vivo while CD9 knockdown enhanced in vivo growth." (PMID 37007105, 2023). "When CD9 is overexpressed, it inhibits the proliferation of hepatoma cells in vitro and in vivo." (PMID 34094979, 2021). "This study aims to investigate the relationship between KLF4 and CD9/CD81 in hepatocellular carcinoma (HCC)." (PMID 32350244, 2020). "Moreover, C1Q+ macrophages in sAH express GPNMB, TREM2, SPP1, and CD9, resembling LAMs, which are reported in liver cirrhosis and hepatocellular carcinoma (HCC)." (PMID 40962953, 2025). "Beyond the head and neck, in hepatocellular carcinoma, tetraspanins CD9 and CD81 are tumor suppressive: CD81 is frequently lost in tumor tissue, and reduced CD9/CD81 expression correlates with advanced stage and poorer outcomes." (PMID 41322905, 2025). "In hepatocellular carcinoma (HCC), Klf4 was shown to regulate the expression of CD9/CD81, exosomal tetraspanin surface proteins that mediate cellular interaction and have been found to be involved in cancer." (PMID 34195082, 2021). "The reported substrates of ZDHHC2 also includes CD9 and CD151 in HEK293 cells, Lck in T cells, and CKAP4 in hepatocellular carcinoma and interstitial cystitis." (PMID 32587588, 2020). "These cells express the marker genes CD9 and TREM2, a tumor suppressor in hepatocellular carcinoma, as well as the markers CAPG and GPNMB." (PMID 33332768, 2020). "Moreover, CD9 knockdown can suppress activation of JNK signaling pathway, which facilitates hepatocellular carcinoma cell proliferation by downstream cyclin D1 and Bcl-2 factors." (PMID 38389703, 2024). "In silico assessment of transcriptomic data within the cancer genome atlas (TCGA) database indicated high expression of CD9 and CD81 in all analyzed tumor sets, while expression of TSPAN8 was elevated in particular in hepatocellular carcinoma and colonic adenocarcinoma." (PMID 36078095, 2022). "As CD9 is the closest homolog of CD81 and showed only low expression levels in hepatoma cells, but slightly higher expression levels in fibroblasts, we decided to investigate whether CD9 can also function as CHIKV host factor." (PMID 35612284, 2022). "To ascertain whether ligation of other cell surface proteins induce hepatoma spread we evaluated antibodies specific for other tetraspanin family proteins (CD9 and CD151) and the non-tetraspanin cell surface expressed protein scavenger receptor B1 (SR-B1)." (PMID 24662676, 2014).
Infertility (14 papers, 2007 to 2024). "CD81 is 44%-sequence identical to CD9 and can partially rescue the infertility of CD9-deficient mouse eggs." (PMID 38666763, 2024). "Several knockouts illustrate their biological functions such as infertility (CD9/CD81), lymphoma development (CD37), immunological deficiency (CD81), or renal insufficiency (CD151)." (PMID 37835445, 2023). "On the other hand, the endometrial stromal cell expression of CD9 has been reported to be associated with infertility related to the endometrium." (PMID 35059465, 2022). "Genetic perturbation suggests that CD9 is required for microvilli formation, which provides an intriguing ultrastructural signature for CD9-associated infertility." (PMID 32931719, 2020). "Furthermore, in the previous study, it was well established that Juno-deficient mice were completely infertile in contrast to CD9-deficient mice, which were only partially infertile." (PMID 25054321, 2014). "CD9, abundantly expressed on the oocyte plasma membrane, is essential for successful sperm–egg fusion, as demonstrated by infertility in CD9 knockout mice despite normal sperm binding and zona pellucida penetration." (PMID 39767756, 2024). "Eight genes that result in male infertility (IZUMO1, SPACA6, TMEM95, TMEM81, SOF1, FIMP, DCST1, and DCST2) and an additional two that cause infertility in females (JUNO and CD9) have been identified." (PMID 38381819, 2024). "The importance of tetraspanins was highlighted by the infertile phenotype of the Cd9 KO female mice, but its molecular function; specifically how CD9 is involved in sperm-egg binding/fusion, has remained poorly understood." (PMID 32231207, 2020). "We recently showed that double knock-out Cd9-/-/Cd81-/- female mice are completely infertile and that, upon fertilization, CD9 tetraspanin controls α6β1 integrin relocation in patches on the egg membrane." (PMID 17850654, 2007). "Defects in CD9 or its associated pathways could explain some cases of unexplained infertility, where sperm binding occurs without successful fusion." (PMID 39767756, 2024). "The ablation of another egg protein, CD9, also leads to a significant impairment in sperm-egg membrane fusion, but its ablation does not cause complete infertility." (PMID 32484434, 2020). "CD9 and CD81, closely related tetraspanins, are expressed abundantly in the lung, and both CD9 knockout (KO) and CD81 KO mice exhibit quite similar phenotypes, such as infertility." (PMID 29572511, 2018). "Interestingly, deletion of both CD9 and CD81 resulted in complete infertility, suggesting indirectly that these two surface molecules are interacting together, suggesting that the specific infertility is just a part of a more complicated situation." (PMID 25054321, 2014). "Ideally, oocytes from women undergoing IVF for nonmale factor infertility could be tested for the presence of CD9." (PMID 20862371, 2010). "Because oocyte CD9 is needed for gamete fusion, measuring the expression of CD9 in women could provide a useful marker for predicting conventional IVF fertilization success in couples with normal sperm parameters, but nonmale factor infertility." (PMID 20862371, 2010).
leukemia (12 papers, 2016 to 2025). A malignant (clonal) hematologic disorder, involving hematopoietic stem cells and characterized by the presence of primitive or atypical myeloid or lymphoid cells in the bone marrow and the blood. "To isolate blast-derived sEV from patients’ plasma, we developed a bioprinted microarray-based immunoassay using monoclonal antibodies (mAbs) specific for leukemia-associated antigens (LAAs) and mAbs specific for a mix of tetraspanins (CD9, CD63, and CD81)." (PMID 38137457, 2023). "Thus, we could consider expression of CD9 as a frequent leukemia‐associated immunophenotype (LAIP) in our study." (PMID 30740913, 2019). "In B-ALL, previous studies have shown a heterogeneous and subtype-specific expression pattern of CD9 while subsequent investigations showed its enrichment in leukemia-initiating cells and involvement in leukemia dissemination." (PMID 38001171, 2024). "Seven leukemia-associated immunophenotype pattern (LAIP) markers, CD9, CD44, CD58, CD73, CD81, CD86, and CD123, were also included in the diagnostic panel." (PMID 39371707, 2024). "For example, our prior work showed that CD9 activates the PI3K/Akt pathway to drive leukemia progression and chemoresistance in BCR::ABL1+ cells." (PMID 38001171, 2024). "According to several studies, it appears that CD9 expression levels on the surface of hematopoietic cells are affected during the occurrence of different types of leukemia." (PMID 33918035, 2021). "In a model of rat basophilic leukemia cells, transfected human CD9 cells degranulate in response to anti-CD9 antibodies co-ligated with FcεRI." (PMID 30356731, 2018). "CD9 was originally described as a surface marker of leukemia and lymphohematopoietic cells; it participates in T cell activation, which serves as the initiation process of the immune response." (PMID 27040083, 2016). "Unexpectedly, varying degrees of CD9+ cells were also found in the bone marrow of mice injected with CD9− cells (21.02%, 4.27–33.9%), which may explain why CD9− mice can also develop leukemia." (PMID 33494824, 2021). "CD9 dimerization is suspected to co-localize on the plasma membrane with the high-affinity IgE receptor (FcεRI), leading to mast cell activation and degranulation as observed on a human CD9-transfected basophilic rat leukemia cell line." (PMID 30356731, 2018). "CD9-positive cells possess CSC characteristics, including drug resistance and migration ability, and promote leukemia progression." (PMID 33494824, 2021). "More importantly, CD9+ cells possess the ability to reconstitute human AML in immunocompromised mice and promote leukemia growth, suggesting that CD9+ cells define the LSC population." (PMID 33494824, 2021). "In conclusion, CD9+ cells display LSC characteristics, exhibit drug resistance, present an increased capacity of migration, and promote leukemia progression." (PMID 33494824, 2021). "The adverse impact of CD9 was confined to specific cytogenetics, notably BCR::ABL1+ rather than KMT2A-rearranged leukemia." (PMID 38001171, 2024).
lymph node metastasis (11 papers, 2011 to 2025). "They proposed that CD9 protein level was inversely associated with lymph node metastasis and the reduction of CD9 was strongly associated with an increasing recurrence risk." (PMID 34222025, 2021). "Lymph node metastasis (LNM) was significantly associated with a high ITGA3/CD9 ratio (high-ITGA3/CD9), tumor size and T3-4, which relate to the extent of tumor invasion, and histopathological mode of invasion (YK4)." (PMID 24006899, 2013). "In ESCC, CD9 expression has been associated with lymph node metastasis." (PMID 40860827, 2025). "However, there have been reports that decreased CD9 expression is associated with lymph node metastasis as well as distant metastasis in some cancers, which will be clarified in future studies." (PMID 34493282, 2021). "CD9 could be a valid prognostic factor for lymph node metastasis risk." (PMID 35563166, 2022). "The expression of CD9 is associated with ESCC staging and lymph node metastasis, and the expression of CD9 in metastatic ESCC tissues is significantly higher than that in non-metastatic tissues, indicating that CD9 is a characteristic of malignant progression." (PMID 40860827, 2025). "In terms of cell motility regulation, CD9, CD63 and CD82 are metastasis suppressors and the expression level is inversely associated with lymph node metastasis." (PMID 34222025, 2021). "A high rate (around 80%) of lymph node metastasis was found in cases with a high ITGA3/CD9 ratio (high-ITGA3/CD9) and invasive histopathology (YK4)." (PMID 24006899, 2013). "Furthermore, the correlation between CD9 and cancer stages or lymph node metastasis also were confirmed (as Stage 4 and N3 only have 2 individuals, Stage 4 and Stage 3 were merged for settlement, and N3 and N2 were merged for calculation)." (PMID 40860827, 2025). "However, in invasive melanoma, as already seen in other tumors, an increase in CD9 correlates with lymph node metastases, distant metastases, and a worse outcome." (PMID 36613587, 2022). "This allows us to infer that CD9 expression is more closely related to distant metastasis that to tumor stage or lymph node metastasis, which may affect prognosis in cancer patients." (PMID 34493282, 2021). "We report here that certain ITGA3/CD9 and ITGB4/JUP gene expression ratios are specifically related to individual clinical events such as lymph node metastasis, primary site recurrence, distant metastasis, and uncontrollable death from OSCC." (PMID 24006899, 2013). "Cox multivariate analysis showed that the largest tumor diameter was ≥2 cm, that lymph node metastasis had occurred, invading the surrounding tissues and organs, and that HMGA2-positive expression or CD9-negative expression was negatively correlated with the postoperative survival time of patients." (PMID 22613496, 2012).
multiple myeloma (11 papers, 2014 to 2025). "Transfection of myeloma cell lines with CD9 also increases their sensitivity to the proteosome inhibitor bortezomib, which is frequently used in the treatment of myeloma, suggesting that loss of CD9 can influence drug resistance." (PMID 25852576, 2015). "DNA methylation in multiple myeloma has been shown to decrease CD9 levels, and recently MYCN and HDAC5 were found to decrease CD9 transcription, leading to invasion and metastasis in neuroblastoma." (PMID 29416746, 2018). "A later retrospective study investigated CD9 expression in bone marrow aspirates from 81 myeloma patients by flow cytometry and discovered that more patients with inactive disease expressed CD9 (60.7%) than those with active disease (33.9%)." (PMID 25852576, 2015). "Interestingly, the transfection of myeloma cell lines with CD9 was reported to increase their susceptibility to lysis by NK and T-cells, offering a potential explanation for how CD9 downregulation could benefit tumor cells." (PMID 25852576, 2015). "In order to study the expression of CD9 and its corresponding cell behavior changes in myeloma cells and their microenvironment, we transfected CD9 in U266 cells and selected the stably transfected cells by flow sorting." (PMID 24788635, 2014). "We found that down-regulation of CD9 by methylation decreased bortezomib sensitivity in multiple myeloma." (PMID 24788635, 2014). "In conclusions, we found that down-regulation of CD9 by methylation decreased bortezomib sensitivity in multiple myeloma." (PMID 24788635, 2014). "The authors also suggested that CD9 be further evaluated as a possible therapeutic target for multiple myeloma in the future." (PMID 24520284, 2014). "In hematological malignancy, CD9 expression has been studied in multiple myeloma and monoclonal gammopathy of unknown significance (MGUS), which precedes myeloma development." (PMID 25852576, 2015). "In addition, myeloma cells with higher levels of CD9 expression proliferate rapidly via interleukin (IL)-16." (PMID 24520284, 2014). "From previous studies, we know that CD9 is considered to function primarily as a progression and metastasis suppressor in a variety of cancers, including breast, non-small cell lung colon and myeloma." (PMID 24520284, 2014). "In order to study the molecular mechanisms of CD9's effects on bortezomib sensitivity in multiple myeloma, we did the genome-wide expression profile microarray to detect the differentially expressed genes and explore the molecular signaling pathways affected by CD9 expression." (PMID 24788635, 2014). "CD9 and CD63 were chosen as their median MFI was similar between healthy and myeloma EV samples and the inclusion of two EV markers would reduce the variability compared to the use of either marker alone." (PMID 36359760, 2022). "The cell and EV lysates from myeloma line RPMI 8226 was positive for CD9 but negative for CD63 and CD81." (PMID 35318648, 2022). "Given the differential expression of CD9 in EVs among the three myeloma cell lines, and the strong CD63 signal in cell lysates, we investigated whether the presence of CD9 and CD63 in EVs was correlated with their expression on the surface of the corresponding cell lines." (PMID 39126063, 2024). "A similar phenomenon is also observed in multiple myeloma, that CD9 may increase tumor proliferation through increasing the ability of the HB-EGF/EGF receptor and CD9 may contribute to the proliferation of tumor cells by associating with HB-EGF on cell membranes." (PMID 24520284, 2014). "Another study revealed that CAF derived exosomes expressing CD9 and CD63 significantly diminished proliferative capacity of myeloma cell lines and lead to improved 5-year disease-free survival in patients bearing CAF derived CD9 positive exosomes compared to CAF derived CD9 negative patients." (PMID 39961904, 2025).
Cirrhosis (10 papers, 2021 to 2026). A chronic disorder of the liver in which liver tissue becomes scarred and is partially replaced by regenerative nodules and fibrotic tissue resulting in loss of liver function. "Macrophage-CD9/IL18 expanded from HBV infection to cirrhosis, while macrophage-CD9/IFI6 expanded from cirrhosis to HCC." (PMID 38116005, 2023). "For example, it shows a new TREM2+CD9+ macrophage subpopulation in human cirrhosis, refines the definition of endothelial subsets, and proposes new therapeutic targets for cirrhosis." (PMID 36387424, 2022). "In chronic settings-including HBV infection, MASLD/MASH, and fibrosis/cirrhosis-we reveal a complex coexistence of functionally opposed subsets that concurrently drive pathology (e.g., CD9 + TREM2 + macrophages) and promote resolution (e.g., CD300E+ macrophages)." (PMID 42058208, 2026). "Additionally, the scar-associated macrophages (SAMs) differentiated by markers such as TREM2, CD9, SPP1, TNFSF12, and LGALS3 and PDGFRA+ myofibroblasts had an increased proportion in patients with cirrhosis." (PMID 39889710, 2025). "Third, we were only able to detect a small number of CD9+/TREM2+ macrophages, indicating that this population is more associated with cirrhosis, as have been shown before, rather than NASH." (PMID 35931712, 2022). "Finally, our scRNAseq analysis shows the presence of DAMs in the liver of NAFLD patients, which share the same phenotype, including expression of TREM2, CD9, GPNMB, MHCII (HLA-DRB1), C1QA, and CLEC10A, as those found in the livers of patients with NASH and cirrhosis." (PMID 38280848, 2024). "The median fibulin‐4/CD9 values increased as liver lesions progressed, with a significant difference between CLD and Child–Pugh class A (P < 0.01), with an AUC of 0.8121, as well as between CLD and Child–Pugh class B‐C cirrhosis (P < 0.01), with an AUC of 0.8995." (PMID 38853023, 2024).
liver cirrhosis (10 papers, 2019 to 2025). "Previous studies identified a macrophage subcluster enriched by CD9 that inhabits the fibrotic niche in liver cirrhosis, termed as scar-associated macrophages." (PMID 38116005, 2023). "In liver disorders, a TREM2+CD9+ subset of monocyte-derived macrophages (also referred to as “scar-associated” macrophages) expands during liver cirrhosis and contributes to pathogenesis." (PMID 35746551, 2022). "The TREM2+CD9+ subset of macrophages that differentiate from circulating monocytes expands during liver cirrhosis and contributes to fibrosis." (PMID 35359989, 2022). "Two recent studies reveal that a novel profibrotic macrophage subset differentiated from circulating monocytes, CD9+TREM2+ macrophage, is significantly increased in patients with liver cirrhosis and plays a key role in activating HSCs at least via releasing TGF-β." (PMID 37415134, 2023).